TIMP3 (TIMP metallopeptidase inhibitor 3)
Diseases named in the same sentence as TIMP3 in open-access papers (continued):
Sharing a sentence is not in itself a finding about the gene and the disease.
melanoma (continued). "Several studies have shown that TIMP3 is able to induce apoptosis in different cell types including retinal pigment epithelial cells, melanoma and prostate cancer cell lines." (PMID 23894681, 2013). "We have previously shown that overexpression of TIMP-1, -2 or -3 inhibits vascular smooth muscle and melanoma cell invasion, while TIMP-3 uniquely promotes apoptosis." (PMID 10188875, 1999). "In addition, overproduction of TIMP-3 reduced melanoma cell attachment to type I/IV collagen and fibronectin, ultimately leading to apoptosis in both SK-Mel-5 and A2058 cells." (PMID 39594665, 2024). "Lastly, with reference to the connection between epigenetic regulation and angiogenesis, a study examined the tissue inhibitor of matrix metalloproteinases-3 (TIMP3), considering that promoter hypermethylation frequently results in decreased TIMP3 levels in melanoma." (PMID 39199614, 2024). "In subsequent in vivo experiments, it was shown that recombinant adenoviral vector carrying the TIMP-3 gene sequence (RAdTIMP-3) when administered to mice with xenograft melanoma line A2058 effectively inhibited gelatinase activity and suppressed tumor growth by inducing apoptosis." (PMID 39594665, 2024). "Consequently, TIMP3 is a promising target for therapeutic intervention as well as a useful prognostic marker, opening the door to future melanoma treatments that will be more effective." (PMID 39199614, 2024). "Melanoma progression and cell migration were inhibited by TIMP-3 expression." (PMID 29467412, 2018). "This study is the first to identify TIMP3 as a potential target of miR-21 in the context of melanoma and demonstrates that down-regulation of TIMP3 may lead to increased melanoma invasion." (PMID 25587717, 2015). "This implicates a decrease in TIMP3 expression as a potential mechanism by which melanomas exhibiting only the radial growth phase may transition to the more aggressive vertical growth phase." (PMID 25587717, 2015). "Notably, one must consider the potential off-target effects of miR-21 when evaluating the role of TIMP3 reductions on the invasion capacity of melanoma cells." (PMID 25587717, 2015). "Additionally, the canonical RECK expression levels positively correlated with TIMP-3 expression, as we have previously reported in a melanoma progression model, and RECK, RECK-B and RECK-I expressions levels correlated positively with TIMP-2." (PMID 26431549, 2015). "Previous work has shown that Timp3 deficiency in the host, not the tumor, alters the growth of implanted melanoma cells." (PMID 25807548, 2015). "However, promoter methylation in primary cutaneous melanomas and metastatic lesions was shown to be a low frequency event, suggesting that the decreased expression of TIMP3 in melanoma must be accomplished through another mechanism of regulation." (PMID 25587717, 2015). "Thus, the miR-21 target TIMP3 promotes apoptosis in melanoma cells by stabilizing three distinct death receptors and activating their apoptotic signaling cascade through caspase-8." (PMID 26116372, 2015). "Notably, TIMP3 exhibits potent antitumor activity in an animal model of melanoma and induces apoptosis in melanoma cells." (PMID 26116372, 2015). "Decreased TIMP3 expression recapitulated this increase in melanoma cell line invasion." (PMID 25587717, 2015). "Little is known about how TIMP3 expression is regulated in melanoma tumorigenesis." (PMID 25587717, 2015). "It was therefore hypothesized that increased levels of miR-21 expression would lead to decreased expression of TIMP3 and thereby enhance the invasiveness of melanoma cells." (PMID 25587717, 2015). "Studies on melanoma cells support the notion that adenoviral TIMP3 alone is able to induce apoptosis by its MMP-inhibitory activity, leading to accumulation, (auto) multimerization, and activation of death receptors even in the presence of limited amount of their ligands." (PMID 23894681, 2013).
melanoma (continued). "This indicates that analog to melanoma cells, TIMP3 overexpression may lead to accumulation and subsequent multimerization and activation of death receptors." (PMID 23894681, 2013). "Moreover, the same authors demonstrated that adenovirally overexpressed TIMP3 inhibits adhesion of melanoma cells to ECM prior to induction of apoptosis." (PMID 23894681, 2013). "This supports the hypothesis that post-transcriptional regulation of TIMP3 is critical in melanoma." (PMID 25587717, 2015). "TIMP3 is sequestered in the extracellular matrix by specifically interacting with sulfated glycosaminoglycans (GAGs) via its N-terminal domain and matrix binding through the N-terminal domain is sufficient for the proapoptotic effect of TIMP3 in melanoma cells." (PMID 23894681, 2013). "Several studies have shown that melanoma cells can express a specific pool of MMPs (MMP-1, MMP-2, MMP-9, MMP-13, and MT1-MMP) as well as their tissue inhibitors (TIMP-1, TIMP-2, and TIMP-3)." (PMID 39594665, 2024). "While the inhibition of miR-21 leads to an increased expression of TIMP-3 and a consequent reduction in the CRC aggressiveness, the overexpression of miR-21 inhibits TIMP-3 in melanoma." (PMID 34199293, 2021). "Nevertheless, overexpression of EphB4 in A375 melanoma cells also influenced expression of 9 angiogenesis-related proteins (Ang-1, VEGF, Akt/PKB, TIMP-1, TIMP-2, TIMP-3, IL-8, TGF-β2, TGF-β R3)." (PMID 33153234, 2020). "In cell-based experiments, TIMP-3 was reported to suppress cell migration and invasion by inhibiting the activity of MMPs and ADAMs in many cancers such as NSCLC, thyroid cancer, melanomas, liver cancer, and colorectal cancer." (PMID 33126605, 2020). "Using an experimental metastasis melanoma model we show that BAG6 is indispensable for the formation of anti-metastatic EVs, which are characterized by the presence of TIMP3, an inhibitor of metalloproteinases involved in the re-modelling of the extracellular matrix." (PMID 31534536, 2019). "Another gene detected with these approaches, TIMP3, is known to inhibit the activity of metalloproteinases, and shows high specificity and selectivity for the ADAM and ADAMTS families that are involved in melanoma cancerous cell development." (PMID 30449276, 2018). "Interestingly, several protease inhibitors, such as TIMP1, TIMP3, and SERPINE2, were also upregulated in metastatic primary melanomas." (PMID 26918341, 2016). "Adenovirally expressed TIMP3 stabilzes tumor necrosis factor receptor-1 (TNF-R1), FAS, and TNF-related apoptosis, inducing ligand receptor-1 (TRAIL-R1) on melanoma cell surface, sensitizing these cells to apoptosis induced by TNF-α, anti-FAS-antibody and TRAIL." (PMID 26116372, 2015). "Altogether, our findings suggest that gastrin may exert both direct and indirect effects on melanoma cells by enhancing their migration and invasion capabilities, possibly by altering the balance towards the dominance of secreted proteases, e.g., MMP-2, against protease inhibitors, e.g., TIMP-3." (PMID 38069171, 2023).
glioma (35 papers, 2010 to 2025). A benign or malignant brain and spinal cord tumor that arises from glial cells (astrocytes, oligodendrocytes, ependymal cells). "Exosome-mediated transport of MIF has been shown to suppress temozolomide resistance in gliomas by modulating the TIMP3/phosphatidylinositol 3-kinase (PI3K)/AKT signaling axis." (PMID 38405130, 2024). "Some studies have shown that pracinostat increases the expression of TIMP3, which plays an important role in inhibiting disease progression in human glioma." (PMID 38774282, 2024). "Mechanistic studies have reported that exosome-derived MIF can enhance the sensitivity of drug-resistant glioma cells to TMZ via repressing the expression of metalloproteinase inhibitor 3 (TIMP3) and subsequently activating the PI3K/AKT signaling pathway." (PMID 35999601, 2022). "Mesenchymal markers, including N-cadherin, slug, snail and metastasis-related genes including MMP2, MMP9 and TIMP3 were widely investigated and verified in glioma remedy mechanisms." (PMID 36234681, 2022). "One further aspect of fibulin-3 pro-tumour signalling in glioma is thought to involve its interaction with TIMP-3." (PMID 32911658, 2020). "In this context, inhibition of angiogenesis by ARF through up-regulation of TIMP3 has been reported in human glioma cells." (PMID 27572316, 2016). "TIMP3 was also verified as a miR-21 target, regulated cancer cells migration, invasion, and apoptosis in different kind of cancers, such as glioma, esophageal carcinoma, renal cell carcinoma and so on." (PMID 27542229, 2016). "MiR-221 also directly inhibits the post-transcriptional expression of metallopeptidase inhibitor 3 (TIMP3), an inhibitor of matrix metalloproteinases (MMPs), and plays an important role in promoting the invasion of human gliomas." (PMID 26416448, 2015). "TIMP3 has been identified as a putative target and has been shown to be decreased in response to miR-21 over-expression in cholangiocarcinoma and glioma." (PMID 25587717, 2015). "Decreased expression of TIMP3 in response to increased miR-21 was first described in cholangiocarcinoma and glioma." (PMID 25587717, 2015). "Having demonstrated TIMP3 as a major target of miR-221/222, we further investigated the correlation of between miR-221/222 and TIMP3 expression in gliomas." (PMID 22681957, 2012). "The present data indicate that miR-221 and miR-222 directly regulate cell invasion by targeting TIMP3 and act as prognostic factors for glioma patients." (PMID 22681957, 2012). "Our present data and previous studies have shown that miR-221/222 affects the behavior of glioma cells including invasion, proliferation, apoptosis and radioresistance, by regulating multiple targets, including TIMP3, p27, PUMA, and PTEN." (PMID 22681957, 2012). "In summary, our data demonstrate that miR-221/222 regulate glioma cell invasion by directly targeting TIMP3." (PMID 22681957, 2012). "As miR-21 regulated TIMP3 expression in glioma and cholangiocarcinoma, we determined baseline TIMP3 protein expression in each of the four breast cancer cell lines relative to miR-21 content." (PMID 20346171, 2010). "This differential pattern suggests a possible tissue- or context-specific regulatory mechanism of TIMP3 in gliomas, which may warrant further investigation." (PMID 41009435, 2025). "The increase in miR-21 expression may cause the inhibitors of matrix metalloproteinase (MMPs), such as RECK and TIMP3 to decrease, leading to elevated MMPs and an increased invasiveness of glioma tumor cells." (PMID 37509289, 2023). "MicroRNA 21 (miR-21) enhances the malignant degree of glioma by inhibiting TIMP3 expression." (PMID 34781885, 2021). "Moreover, the high levels of miR-21 in U87 GSCs are able to prevent glioma cell apoptosis by inhibiting the tissue inhibitor of metalloproteinases 3 (TIMP3) gene, a suppressor of malignancy and inhibitor of matrix metalloproteinases (MMPs)." (PMID 33348804, 2020).
glioma (continued). "In our study, down-regulation of TIMP3 correlated with increasing malignancy in human gliomas." (PMID 22681957, 2012). "There was an inverse relationship between miR-221/222 and TIMP3 levels in glioma tissues." (PMID 22681957, 2012). "Repression of miR-221 by a peptide nucleic acid could contribute to growth inhibitory effects via significant increase in p27 and TIMP3, thereby suggesting that sequence-selective targeting against miR-221 might have the potential for the treatment of human gliomas." (PMID 28261196, 2017). "Glioblastoma multiforme (GBM) and lower-grade glioma (LGG) exhibited markedly higher TIMP3 expression compared to their corresponding normal tissues, in contrast to most other tumor types, where TIMP3 expression was lower than in adjacent normal tissues." (PMID 41009435, 2025). "Upregulation of metalloproteinase inhibitor 3 (TIMP3) and inhibition of the PI3K/ACT signalling pathway and knockdown of MIF resulted in a significant increase in susceptivity of drug‐resistant glioma cells to TMZ." (PMID 39950738, 2025). "In gliomas, hsa-miR-21-5p downregulates PDCD4 and TIMP3, facilitating tumor growth and resistance to apoptosis, making it a marker of poor prognosis." (PMID 40362695, 2025). "The oncogenic effect of miRNA-21 in human glioma cells is implemented through the suppression of such tumor suppressor genes as TAp63, HNRPK, JMY, TOPORS, RECK, TP53BP2, TIMP3, PDCD4, and TGFBR2/3." (PMID 37033545, 2023). "For example, KDM1A promotes cell invasion through silencing the TIMP metallopeptidase inhibitor 3 (TIMP3) in non-small lung cancer, inhibits cell apoptosis in glioma, and promotes cell proliferation in neuroblastoma." (PMID 33987474, 2020). "Ectopic expression of TIMP3 inhibited U251 and LN229 glioma cell invasion through the inhibition of MMP2 and MMP9 expression and activity." (PMID 22681957, 2012). "Further, qRT-PCR and Western blot analysis showed CLEC19A overexpression could reduce the expression levels of PI3K, VEGFα, MMP2, and NF-κB and increase PTEN, TIMP3, RECK, and PDCD4 expression levels in glioma cell lines." (PMID 38167030, 2024). "In glioblastoma, inhibition of miR-21 leads to upregulation of the matrix metalloproteinase inhibitors, a reversion inducing cysteine-rich protein with Kazal motifs (RECK), and TIMP metallopeptidase inhibitor 3 (TIMP3), which decreases glioma motility and activates caspases." (PMID 36139366, 2022). "Fibulin-3 inhibition of TIMP-3 relieves TIMP-3 suppression of ADAM17, which subsequently may enhance glioma angiogenesis via downstream activation of endothelial tabulation and pro-invasive NF-κB signalling." (PMID 32911658, 2020). "In addition, miR-21 promotes glioma invasion by targeting RECK and TIMP3 genes, which are suppressors of malignancy and inhibitors of matrix metalloproteinases." (PMID 27803763, 2016). "MiRNA-21 exerts its oncogenic function in gliomas through its post-transcriptional targets and downstream signal pathways: PDCD4, phosphatase and tensin homolog (PTEN), tumour protein 63 (TP63), tropomyosin 1 (TPM1), and tissue inhibitor of metalloproteases 3 (TIMP3)." (PMID 33610185, 2021). "However, MALAT1 had little effect on the expression of TIMP3 (data not shown), further indicating that the mechanism of MALAT1-suppressed glioma cell invasion is via downregulation of expression of MMP2 at the protein level." (PMID 26938295, 2016).
Sorsby fundus dystrophy (33 papers, 2007 to 2024). A rare progressive autosomal dominant macular dystrophy, presenting between the third and sixth decades of life, characterized by retinal atrophy and retinal detachment and leading to loss of central vision, then peripheral vision, and eventually blindness. "We aim to report the ocular phenotype and molecular genetic findings in two Czech families with Sorsby fundus dystrophy and to review all the reported TIMP3 pathogenic variants." (PMID 38612555, 2024). "As with AMD, lipid-rich deposits also accumulate with mutations in Timp3 that cause Sorsby’s fundus dystrophy (SFD), but with an earlier onset of symptoms." (PMID 39276938, 2024). "In humans, the mutations in TIMP3 are responsible for Sorsby fundus dystrophy (SFD), an autosomal, dominant, and inherited retinal dystrophy." (PMID 36982446, 2023). "Patients with Sorsby fundus dystrophy (an autosomal dominant disorder associated with variants in the TIMP3 gene) also usually have subjective dark adaptation impairment, demonstrable psychophysically." (PMID 35612091, 2022). "Sorsby fundus dystrophy (SFD) is an autosomal dominant IRD caused by variants in the tissue inhibitor of metalloproteinases‐3 (TIMP3) gene." (PMID 35739648, 2022). "For example, mutations in collagen are implicated in ocular abnormalities such as Knobloch’s and Alport syndrome, whilst TIMP-3 mutations are directly linked with Sorsby fundus dystrophy (SFD)." (PMID 31877820, 2019). "Mutations in TIMP3 were implicated in Sorsby's fundus dystrophy (SFD), an autosomal dominant disorder featuring accumulation of macular drusen and progression to CNV and retinal degeneration." (PMID 31583032, 2019). "This is also the site of interaction of Fib3 with another ECM protein, TIMP3 which itself is mutated in Sorsby fundus dystrophy, another inherited disease which has similarities to macular degeneration, and is also associated with AMD." (PMID 23840815, 2013). "Defects in TIMP3 are the cause of Sorsby fundus dystrophy (OMIM 136900), a rare autosomal dominant macular disorder with age of onset in the fourth decade." (PMID 21976959, 2011). "Genetic mutations in the TIMP3 gene result in Sorsby fundus dystrophy (SFD), a rare, dominantly inherited, adult-onset retinal dystrophy clinically and histopathologically related to age-related macular degeneration, the most common cause of blindness in adults." (PMID 31798396, 2019). "Furthermore, mutations in Timp3 have been associated with Sorsby’s fundus dystrophy, an autosomal dominant maculopathy with submacular choroidal neovascularization." (PMID 29514656, 2018). "Indeed specific mutations in TIMP-3 result in the autosomal dominant degenerative disease of the macula, Sorsby’s fundus dystrophy (SFD), frequently characterized by abnormal retinal vascularization." (PMID 24129822, 2014). "Tissue Inhibitor of Metalloproteinase (TIMP3) encodes a matrix TIMP3 inhibitor that is involved in the regulation of extracellular matrix (ECM) degradation and is associated with senescence and Sorsby fundus dystrophy." (PMID 37728589, 2024). "Sorsby fundus dystrophy (SFD, OMIM #136900) is an autosomal dominant MD with complete penetrance caused by pathogenic variants in the TIMP3 (tissue inhibitor of metalloproteinase 3) gene, located on chromosome 22q12.3." (PMID 38732293, 2024). "Mutant TIMP-3 expressing mice had symptoms of Sorsby Fundus Dystrophy with reduced MMP inhibitory capability and increased MMP-2 activity showing dysregulation of elastin degrading proteases was responsible for disease pathology." (PMID 37001705, 2023). "A notable MMP9 partner is TIMP3, which we and others have shown to be linked with AMD as well as with Sorsby fundus dystrophy." (PMID 36498929, 2022). "Interestingly, mutation in the TIMP3 gene has been linked to the AMD-like disease Sorsby fundus dystrophy (SFD)." (PMID 35453951, 2022).
Sorsby fundus dystrophy (continued). "Sorsby’s fundus dystrophy (SFD) is a rare, late-onset macular dystrophy caused by mutations in the TIMP3 gene." (PMID 35207132, 2022). "TIMP3 is secreted by RPE basally to remodel Bruch’s membrane, inhibit angiogenesis and regulate inflammation, and mutations and deficiencies in TIMP3 have been linked to various retinal degenerative diseases including AMD and Sorsby’s fundus dystrophy." (PMID 32842471, 2020). "Rare TIMP-3 risk alleles and mutations are directly linked with retinopathies such as age-related macular degeneration (AMD) and Sorsby fundus dystrophy, and potentially, through indirect mechanisms, with Alzheimer’s disease." (PMID 31877820, 2019). "For example, TIMP-3 mRNA was significantly up-regulated in human RP and Sorsby’s fundus dystrophy conditions." (PMID 29742163, 2018). "Fibulin-3 minimally interacts directly with ECM components such as elastin or fibrillin-1 however it strongly regulates TIMP-3, indicating reduction of fibulin-3 may increase aberrant elastic fiber degradation through protease/anti-protease imbalance in a similar manner to Sorsby Fundus Dystrophy." (PMID 37001705, 2023). "Interestingly, a short 16 amino acid peptide sequence, that forms the truncated C-terminus of a mutant form of TIMP-3, E139X, known to give rise to the degenerative retinal disease, Sorsby’s fundus dystrophy, also inhibited VEGF receptor-mediated signalling by endothelial cells (EC) in vitro." (PMID 24129822, 2014).